GGTLC2 (gamma-glutamyltransferase light chain 2)
Synonyms: GGTL4
Tractability: No criterion of Open Targets' tractability assessment is met for any kind of drug.
Gene: Protein-coding gene on chromosome 22 (22,644,614 to 22,647,898, forward strand). Ensembl gene ENSG00000100121.
Gene Ontology:
Molecular function: protein binding; glutathione hydrolase activity
Biological process: leukotriene D4 biosynthetic process; glutathione catabolic process
Cellular component: extracellular exosome
Genetic constraint (gnomAD): Loss-of-function variants: 12 observed, 15.69 expected, observed/expected ratio (o/e) 0.77, 90% interval 0.49 to 1.24. The upper end of that interval is the gene's LOEUF score, 1.24, which puts it in group 5 of 6, group 1 being the genes least tolerant of losing a copy. Missense variants: 188 observed, 223.55 expected, observed/expected ratio (o/e) 0.84, 90% interval 0.75 to 0.95. Synonymous variants: 84 observed, 96.27 expected, observed/expected ratio (o/e) 0.87, 90% interval 0.73 to 1.05.
Homologues: Orthologues: dog GGT1 (82% identical), chimpanzee GGTLC2 (80% identical), rat Ggt1 (77% identical), mouse Ggt1 (73% identical), zebrafish ggt1a (59% identical), zebrafish ggt1b (52% identical), zebrafish ggt1l2.2 (41% identical), zebrafish ggt1l2.1 (40% identical), Drosophila melanogaster Ggt-1 (39% identical), zebrafish si:dkey-222h21.12 (39% identical), tropical clawed frog ggt1 (38% identical), zebrafish si:ch73-236c18.3 (38% identical), and 2 more. Paralogues in human: GGT1 (92% identical), GGTLC1 (89% identical), GGTLC3 (86% identical), GGT5 (36% identical), GGT7 (28% identical), GGT6 (13% identical).
Diseases named in the same sentence as GGTLC2 in open-access papers:
GGTLC2 is named in the same sentence as 5 diseases in open-access papers, as found by Europe PMC text mining. Sharing a sentence is not in itself a finding about the gene and the disease. The quoted sentences say what the papers report.
sarcoma (2 papers, 2022 to 2025). A usually aggressive malignant neoplasm of the soft tissue or bone. "GGTLC2, a member of the GGT family, has been demonstrated in previous studies to play a significant role in the prevention and diagnosis of sarcomas." (PMID 40191433, 2025). "GGTLC2, a constituent of the GGT family, has been characterized as an antioxidant gene, with emerging evidence indicating a potential link between its expression levels and sarcoma patient outcomes." (PMID 40191433, 2025).
prostate carcinoma (1 paper, 2025). A carcinoma that arises from epithelial cells of the prostate gland. "Our results showed that GGT1/5/6/7 genes are the predominant isoforms while GGTLC1/2/3 is expressed at a very low level in prostate tissues, although there are some outliers with higher levels of GGTLC2 in primary prostate cancers." (PMID 40094020, 2025).
tumor (1 paper, 2025). "In vivo experiments demonstrated that tumor size and weight significantly increased in the GGTLC2 overexpression group compared to the vector group, while the crocin treatment group exhibited a significant reduction." (PMID 40191433, 2025). "Discussion: In conclusion, our findings suggest that crocin, as a promising natural compound for GC therapy, may inhibit ferroptosis in GC cells through the Nrf2/GGTLC2 signaling pathway, thereby suppressing tumor initiation and progression." (PMID 40191433, 2025). "Additionally, the expression profiles of GGTLC2 and Nrf2 in xenograft tumor tissues were assessed." (PMID 40191433, 2025).
GGTLC2 also shares sentences with these, for which no sentence is quoted: gastric cancer (1 paper); lung carcinoma (1).